HIF1A (hypoxia inducible factor 1 subunit alpha)
Diseases named in the same sentence as HIF1A in open-access papers (continued):
Sharing a sentence is not in itself a finding about the gene and the disease.
tumor (continued). "Energetically exhausted tumor foci most likely represent a transient condition but at the same time relish protection triggered by HIF-1α and by the local environment." (PMID 40362659, 2025). "Although the role of miR-182 in tumor development is controversial, its carcinogenic function by promoting HIF-1α activation has been widely reported." (PMID 40171017, 2025). "Even more exciting, in live animal models (VEGFR2-luc transgenic mice implanted with 4T1 cells), antagomir-21 slowed tumor angiogenesis—basically cutting off the tumor’s blood supply—by blocking the HIF-1α/VEGF/VEGFR2 pathway." (PMID 40167762, 2025). "While YY1 promotes tumor growth by stabilizing HIF-1α levels in some types of tumors, aberrant expression of YY1 results in ccRCC by increasing the expression of HIF-2α and inhibiting VHL." (PMID 40688406, 2025). "Second, PFKFB3 is highly expressed in endothelial cells and promotes tumor angiogenesis by activating the HIF-1α/VEGF pathway." (PMID 40438141, 2025). "In mouse tumor models under hypoxic conditions, the growth of tumors in HIF‐1α knockout mice is suppressed." (PMID 40959206, 2025). "Our study found that increased HIF-1α expression in the tumor microenvironment was correlated with decreased progression-free survival (PFS), although stromal HIF expression showed no significant impact on overall survival." (PMID 39857068, 2025). "HBV also regulates the ubiquitination of pVHL, inhibiting its degradation of HIF‐1α, promoting angiogenesis, and aiding tumor cells in evading immune surveillance." (PMID 40060195, 2025). "Blocking critical signaling pathways in HCC, such as STAT3/VEGF/HIF-1α.Prevent tumor growth and angiogenesis.Cell cycle arrest, especially in the S phase." (PMID 40430962, 2025). "Tumor cells located within hypoxic regions exhibit heightened levels of hypoxia-inducible factor alpha (HIF-1α)." (PMID 41313526, 2025). "The HIF-1α pathway modulates key biological processes such as glycolysis, cell proliferation, migration, and angiogenesis, which are essential for tumor survival and progression." (PMID 41210694, 2025). "As EC progresses, the tumor microenvironment gradually develops a hypoxic state, leading tumor cells to regulate metabolism by activating hypoxia-inducible factor-1α (HIF-1α) to adapt to adverse conditions." (PMID 40264788, 2025). "HIF-1α not only promotes angiogenesis and cell proliferation but also enhances cancer cell survival and migration, ultimately accelerating tumor invasion and metastasis." (PMID 40429879, 2025). "Compared with YFJDT + oe‐NC, HIF1A overexpression was beneficial to tumor growth, and erastin inhibited tumor growth." (PMID 39912781, 2025). "In summary, HIF-1α is instrumental in the anti-tumor effects of anlotinib and bevacizumab and appears to account for the contribution made by the latter to the combination therapy." (PMID 41041327, 2025). "In lymphoma models, curcumin downregulates LDHA activity and expression by targeting the c-Myc and HIF-1α signaling pathways, thereby reducing glycolysis and inhibiting tumor progression." (PMID 41515171, 2025). "MCT1, proven as a key regulator of lactate exchange between tumor cells, serves as an HIF-1α inhibitor when blocked." (PMID 41181157, 2025). "Hypoxia has immunosuppressive effects within the tumour microenvironment and affects the expression of immune checkpoint molecules by activating HIF-1α, regulating glycolysis and the Ado-A2a receptor (A2aR) axis, and driving EMT." (PMID 40647497, 2025). "HIF-1α also upregulates immune checkpoint molecules such as PD-L1 on tumor cells, directly inhibiting T cell activity." (PMID 41048631, 2025). "It has been established a relationship between HIF1α and tumour cell proliferation, invasion, metastasis, recurrence, and vascular proliferation of HCC." (PMID 41007296, 2025). "Preclinical studies have shown that HIF-1α inhibitors exert anti-tumor effects by inhibiting genes related to glycolysis, angiogenesis, and metastasis in tumor cells." (PMID 41041327, 2025).
tumor (continued). "Collectively, our findings position the WWOX/HIF1A axis as a master regulator of tumour-immune dynamics, whose disruption drives immune escape through context-dependent mechanisms." (PMID 41007296, 2025). "The elevated production of HIF-1α is a significant factor enabling tumor cells to endure in hypoxic or even anaerobic conditions and proliferate rapidly." (PMID 41154694, 2025). "Copper-induced cell death promotes tumor angiogenesis and immune evasion by activating pathways such as HIF-1α and NF-κB." (PMID 41185600, 2025). "Our analysis revealed a hypoxic inner region characterized by nuclear HIF1α localization in three‐dimensional cultured tumor spheroids, which was notably decreased in CAPN2 knockdown tumor spheroids." (PMID 40151834, 2025). "As a downstream effector of this pathway, mTOR not only promotes protein synthesis and metabolic reprogramming but also enhances tumor cell tolerance and invasiveness by regulating HIF-1α." (PMID 40303931, 2025). "There are several treatment strategies that have emerged within target hypoxia-driven tumor biology, especially the HIF-1α pathway and its downstream mediators." (PMID 40507913, 2025). "Under hypoxic conditions, AKT stabilizes HIF-1α, enhancing tumor cell survival while inducing VEGF secretion and promoting angiogenesis." (PMID 40438678, 2025). "Quantification of tumor area and number per kidney further supported that PRCC‐TFE3 KI/Hif1α KO tended to inhibit tumor development." (PMID 39807625, 2025). "It is possible that HIF-1α flexibly regulates adhesion proteins such as DSG2 at different stages of tumor metastasis." (PMID 41381723, 2025). "While in the hypoxic tumor microenvironment, in contrast to the effects of HIF-2α, upregulation of HIF-1α in tumor cells enhances ferroptosis resistance by increasing cystine uptake, promoting SLC7A11 transcription, and lipid droplet formation." (PMID 40169575, 2025). "In hypoxia, HIF-1α activation is crucial for multiple tumor development processes, including proliferation, apoptosis, invasion, angiogenesis, metabolism, immunity, and treatment resistance." (PMID 40860815, 2025). "The same HIF-1α–VEGF axis that drives vessel formation can enhance tumor invasiveness through epithelial–mesenchymal transition (EMT) and extracellular matrix degradation." (PMID 41311849, 2025). "Through its regulation of key signaling pathways such as JAK/STAT, mTORC1/HIF-1α, and mTORC2/PPARγ, dioscin effectively inhibits tumor progression while alleviating inflammation and promoting tissue repair." (PMID 40417220, 2025). "Target genes of HIF-1α are related to tumor progression, affecting proliferation, angiogenesis, and metastasis." (PMID 40746883, 2025). "Our findings suggest that the increased HIF-1α, LOX and ITGA5 expression in the tumor microenvironment is associated with decreased PFS, potentially reflecting resistance to treatment." (PMID 39857068, 2025). "For instance, Glucose Transporter 1 (GLUT-1)-expressing cancer cells were found at the tumor edge, while HIF-1α was enriched in the tumor center." (PMID 40746883, 2025). "Mechanistically, it interferes with pro-survival autophagic signaling by inhibiting the PI3K/AKT/mTOR pathway and activating the c-Jun N-terminal kinase cascade, thereby reducing HIF-1α expression, a key regulator of tumor progression under hypoxia." (PMID 40869364, 2025). "This suggests that ART exerts an inhibitory effect on tumor growth and CM by down-regulating the HIF-1α/VEGF/PDGF signaling pathway." (PMID 41160271, 2025). "As the tumor grows, it promotes a hypoxic environment, leading to the increased production of HIF-1α." (PMID 40244228, 2025). "HIF-1α is a transcription factor that becomes stabilized under hypoxic conditions, which are commonly found in the tumor microenvironment." (PMID 40507229, 2025).
tumor (continued). "The stabilization of HIF-1α is the cornerstone of the cellular response to low oxygen, coordinating a profound transcriptional shift that promotes tumor survival, metabolic reprogramming, and metastasis." (PMID 41302515, 2025). "Targeting HIF-1α represents a promising strategy to overcome the immunosuppressive and tumor-promoting effects of the hypoxic IVM." (PMID 39981236, 2025). "Another study in Nature Medicine in 2024 further discovered that HBOT upregulates miR-210-3p to suppress HIF-1α translation, thereby inhibiting tumor angiogenesis and enhancing sensitivity to radiotherapy." (PMID 40552269, 2025). "Beyond metabolic adaptation, HIF-1α activity enhances tumor cell migration, angiogenesis, immune evasion, and resistance to conventional therapies, including chemotherapy and radiation." (PMID 40647184, 2025). "A key contributing factor is the hypoxic microenvironment induced by TACE, which activates HIF1α in residual tumor cells." (PMID 41467954, 2025). "For example, ID can facilitate tumor cell adaptation to adverse microenvironments by stabilizing HIF-1α." (PMID 41190142, 2025). "In our study, HIF-1α overexpression significantly correlated with advanced tumor staging and greater DOI." (PMID 40546546, 2025). "Our study comprehensively examined the hypoxia pathway in the tumor microenvironment, focusing on the expression of HIF-1α, LOX and ITGA5 and their prognostic implications." (PMID 39857068, 2025). "Fluorescence microscopic data showed immunofluorescence (IF) staining of hypoxia-inducible factor (HIF)-1α, a key marker of hypoxia and which plays a critical role in tumor progression and therapy resistance." (PMID 40514659, 2025). "Under the combined influence of hypoxia and ID, tumor cells adjust metabolic reprogramming-related target genes via the HIF-1α pathway, promoting cancer progression." (PMID 41190142, 2025). "For instance, nanoparticles loaded with HIF-1α inhibitors or oxygen-releasing agents can deliver their payload selectively to hypoxic tumor regions, minimizing off-target effects." (PMID 39981236, 2025). "HIF1A, a key factor in hypoxia adaptation, showed reduced expression, further indicating impaired tumor growth under hypoxic conditions." (PMID 41411347, 2025). "In prostate cancer, lactate activates KIAA1199 via HIF-1α-mediated lactylation, driving angiogenesis, vasculogenic mimicry, and hyaluronic acid depolymerization, ultimately accelerating tumor progression." (PMID 40433363, 2025). "Specifically, when cultured under normoxic conditions, HIF-1α expression in TAMs is stabilized by tumor-derived lactate, leading to the transcription of the VEGFA gene." (PMID 40760493, 2025). "Hypoxia-inducible factor-1α (HIF-1α) is an important transcriptional regulator in response to a hypoxic environment and is crucial in the adaptation of tumor cells to the hypoxic environment." (PMID 41585262, 2025). "HIF-1α also impairs NO signaling, increases tumor cell-platelet interactions, regulates CD47 expression to prevent phagocytosis and drives VEGF-mediated angiogenesis, facilitating metastasis and immune escape." (PMID 41048631, 2025). "During tumor growth, HIF-1α regulates the activity of various transcription factors and their downstream molecules by modulating various biological processes, including cell proliferation, growth, angiogenesis, and metastasis." (PMID 41585262, 2025). "Due to its role in collagen synthesis, collagen fibre alignment, and ECM interactions within the TME, HIF-1α facilitates tumor cell migration and metastasis." (PMID 41313526, 2025). "HIF-1α plays a pivotal role in tumor metabolism by promoting glycolysis through the upregulation of GLUT1, HK2, and LDHA." (PMID 41281744, 2025). "Noman and coauthors reported that HIF-1α directly drives the expression of programmed cell death ligand (PD-L1), thus helping tumor cells evade immune surveillance." (PMID 40507913, 2025).
tumor (continued). "Recent investigations have demonstrated that Andro effectively regulates the tumor angiogenic TGF‐β1/prolyl hydroxylase 2 (PHD2)/HIF‐1α/VEGF signaling pathway." (PMID 40584407, 2025). "Markers such as GLUT-1, HIF-1α, FASN, LAT-1, and CA9 have been associated with tumor aggressiveness, metastasis, and poor prognosis, particularly in PanNENs." (PMID 41458541, 2025). "The WWOX/HIF1A transcription ratio has emerged as a critical biomarker in cancer prognosis, offering valuable insights into tumour biology and informing therapeutic strategies." (PMID 41007296, 2025). "Biologically, rapid tumor proliferation often leads to local hypoxia, which stabilizes hypoxia-inducible factor-1 alpha (HIF-1α), thereby activating downstream signaling pathways." (PMID 41229502, 2025). "Digoxin is a HIF inhibitor that blocks HIF-1α protein accumulation and inhibits primary tumor growth, as well as lymph node and lung metastasis, of MDA231 cells implanted in the mammary fat pad of immunodeficient mice." (PMID 40662366, 2025). "The PI3K-Akt signaling pathway stimulates cell proliferation and tumor invasion while upregulating hif-1α translation, thereby enhancing hif-1α-mediated gene expression." (PMID 41445673, 2025). "Combined with HIF-1α inhibitor digoxin, 3IZH further reduces HIF-1α resistance, enhances immune cell infiltration, and shows satisfying efficacy in bilateral tumor-bearing mice." (PMID 41387306, 2025). "The STAT3/HIF‐1α/VEGF signaling pathway plays significant roles in promoting tumor growth and progression, such as regulating cellular responses to low oxygen levels (hypoxia) and promoting the expression of genes that support tumor growth and angiogenesis." (PMID 40860906, 2025). "Hypoxia forces a shift away from mitochondrial ATP production, while tumor cell anaerobic metabolism is facilitated by rapid tumor cell glucose uptake as a result of HIF-1α induced up-regulation of glucose transporters." (PMID 41479781, 2025). "TZP also delayed tumor development in a patient‐derived xenograft (PDX) mouse model accompanied by HIF‐1α mediated PFKFB3‐PFK‐1 inhibition." (PMID 40125821, 2025). "The specific effect of EC Tert-KO promoting metastatic dissemination of PDAC cells is likely due to a particularly strong tumor hypoxia induction in this model, evident from a striking HIF1a activation and nuclear localization." (PMID 40482194, 2025). "Exosomes have emerged as a novel source of noninvasive tumor biomarkers, in addition to hypoxia-inducible factor 1 subunit alpha (HIF-1a)." (PMID 40305328, 2025). "HIF-1α has been established as the most important regulatory element in the hypoxic responses of tumor cells." (PMID 41189947, 2025). "In these proliferative tumor sections, HIF-1α is predominantly expressed in the nuclei of endothelial and stromal cells." (PMID 40443737, 2025). "The results demonstrate that TNBCvax significantly inhibits and delays tumor development compared to the CpG group and other single vaccine-treated groups, including HIF-1α, IGF-1R, and TOP2A." (PMID 40969744, 2025). "The hypoxic tumor microenvironment activates hypoxia-inducible factor 1 alpha (HIF-1α), upregulating VEGF expression." (PMID 40568594, 2025). "HIF-1α, a key regulator of the hypoxic response, not only boosts glycolytic activity but also stimulates the expression of PD-L1 on both tumor and stromal cells." (PMID 39897050, 2025). "Loss of the tumour suppressive role of the VHL protein (pVHL) leads to accumulation and constitutive activation of hypoxia inducible factor 1α (HIF-1α), which is responsible for the metabolic switch that allows survival of cells in the hypoxic environment." (PMID 40869272, 2025).
tumor (continued). "Hypoxia contributes to tumor radioresistance in RC by hypoxia-inducible factor 1-alpha (HIF-1α) upregulation in response to low oxygen levels, promoting cell survival and tumor progression." (PMID 39885557, 2025). "Hypoxic conditions within the tumor microenvironment also induce GPER upregulation via HIF-1α in an EGFR/ERK dependent manner." (PMID 40641933, 2025). "For example, a high co-expression of PD-L1 and hypoxia-inducible factor-1α (HIF-1α) has been documented in pulmonary pleomorphic carcinoma, where it correlates with tumor necrosis and poor prognosis." (PMID 40458414, 2025). "Hypoxia probe detection in tumor-bearing mice reveald low oxygen partial pressure in tumor tissues, accompanied by high expression of HIF1α and HIF2α." (PMID 40290443, 2025). "Hypoxia determinants such as HIF-1α and HIF-2α are found in both the tumor epithelium and tumor-associated stroma." (PMID 39857068, 2025). "Functional studies demonstrated that NRP1 is a key effector mediating HIF-1α-induced tumor migration, invasion, and VM formation, and that targeting the HIF-1α-induced overexpression of NRP1 can inhibit the malignant progression of LUAD." (PMID 41019994, 2025). "Meanwhile, tumor cell-derived VEGF and HIF-1α promote angiogenesis through endothelial activation, supplying oxygen and nutrients to the tumor." (PMID 41476608, 2025). "This hypoxia-driven exosomal release is often HIF-1α-dependent and occurs alongside acidic pH–mediated exosome uptake, creating a highly efficient communication network for tumor survival and immune evasion." (PMID 40427384, 2025). "Parkin also counteracts the hypoxic response, essential for tumor survival and angiogenesis, by mediating the degradation of hypoxia‐inducible factor 1α (HIF‐1α)." (PMID 41362701, 2025). "Moreover, ROS affect various stages of carcinogenesis: they initiate tumor formation by causing DNA mutations, promote tumor growth through the inhibition of apoptosis, and support cancer progression via the activation of transcription factors such as NF-κB and HIF-1α." (PMID 40361452, 2025). "To verify the efficacy of HS-ICTO in alleviating tumor hypoxia, we performed HIF-1α immunofluorescence staining." (PMID 40610512, 2025). "Hypoxia-inducible factor-1α (HIF-1α) and c-Myc are two key transcription factors that maintain high-level glycolysis in tumor cells." (PMID 40034817, 2025). "For example, in ccRCC, the respective pro-oncogenic role and tumor-suppressive role of HIF-1α and HIF-2α are well established, but the recent development of a mouse model for this disease has questioned this concept." (PMID 41413686, 2025). "The accumulation of HDAC4 in the nucleus reduces the acetylation level of HIF1α, enhancing the stability and transcriptional activity of HIF1α and increasing the adaptability of tumour cells to hypoxic environments." (PMID 39778006, 2025). "Visibly, these nanodrugs can modulate the HIF-1α pathway to repolarize TAMs from pro-tumor M2 to anti-tumor M1 phenotypes, thus boosting the immune response against cancer." (PMID 40302816, 2025). "The hypoxia‐related pathway is known to be regulated by the transcription factors HIF1α and HIF2α, which contribute to tumor development in various cancers including ccRCC (Kaelin Jr." (PMID 39807625, 2025). "The regulatory influence exerted by HIF-1α on the SOX2/OCT4 signaling pathway plays a significant role in tumor cell self-renewal and differentiation." (PMID 39781344, 2025). "In SM, in which characteristically the peritheliomatous pattern (cell cuff surrounding a vessel) is observed, most of the HIF‐1α positive cells were located at the periphery of the tumor." (PMID 40867038, 2025). "Targeting calpain activity has been proposed as a potential strategy to reduce HIF-1α–mediated tumor aggressiveness." (PMID 41462905, 2025). "The results demonstrate that, compared to the HS group, the expression levels of HIF-1α protein in tumor tissue within the HS-ICTO group are significantly reduced." (PMID 40610512, 2025).